CKAP2L (cytoskeleton associated protein 2L)
Description:
Microtubule-associated protein required for mitotic spindle formation and cell-cycle progression in neural progenitor cells.
Synonyms: Radmis; FLJ40629
Tractability: PROTAC: UniProt records ubiquitination sites on it; ubiquitination databases record sites on it.
Gene: Protein-coding gene on chromosome 2 (112,736,349 to 112,764,664, reverse strand). Ensembl gene ENSG00000169607.
Subcellular location: Cytoplasm, cytoskeleton, spindle pole
Subcellular location (Human Protein Atlas): Microtubules; Cytosol; Mitotic spindle; Primary cilium
Gene Ontology:
Cellular component: centrosome; microtubule cytoskeleton; mitotic spindle; spindle pole
Genetic constraint (gnomAD): Loss-of-function variants: 29 observed, 54.9 expected, observed/expected ratio (o/e) 0.53, 90% interval 0.39 to 0.72. The upper end of that interval is the gene's LOEUF score, 0.72, which puts it in group 2 of 6, group 1 being the genes least tolerant of losing a copy. Missense variants: 828 observed, 826.57 expected, observed/expected ratio (o/e) 1, 90% interval 0.94 to 1.06. Synonymous variants: 297 observed, 302.92 expected, observed/expected ratio (o/e) 0.98, 90% interval 0.89 to 1.08.
Homologues: Orthologues: chimpanzee CKAP2L (99% identical), macaque CKAP2L (91% identical), dog CKAP2L (75% identical), pig CKAP2L (73% identical), rabbit CKAP2L (71% identical), guinea pig CKAP2L (70% identical), mouse Ckap2l (64% identical), rat Ckap2l (62% identical), tropical clawed frog ckap2l (29% identical), zebrafish ckap2l (18% identical). Paralogues in human: CKAP2 (21% identical).
Diseases named in the same sentence as CKAP2L in open-access papers:
CKAP2L is named in the same sentence as 34 diseases in open-access papers, as found by Europe PMC text mining. Sharing a sentence is not in itself a finding about the gene and the disease. The quoted sentences say what the papers report.
glioma (7 papers, 2020 to 2022). A benign or malignant brain and spinal cord tumor that arises from glial cells (astrocytes, oligodendrocytes, ependymal cells). "On the other hand, CKAP2L expression increases with the grade of glioma and is associated with a poorer prognosis." (PMID 36090903, 2022). "Cox regression analysis indicated that CKAP2L can serve as an independent risk factor but also has relatively reliable diagnostic value for the prognosis of glioma patients." (PMID 34631884, 2021). "Kaplan-Meier curves demonstrated that increased CKAP2L expression was closely associated with poor prognosis of glioma patients." (PMID 34631884, 2021). "The study results demonstrate that CKAP2L expression increases with the grade of glioma and is associated with poor prognosis of glioma patients." (PMID 34631884, 2021). "Further, Kaplan-Meier plots revealed that increased expression of CKAP2L was associated with shorter survival time of glioma patients in datasets retrieved from multiple databases." (PMID 34631884, 2021). "CKAP2L, an independent risk factor, is closely related to glioma prognosis." (PMID 36158120, 2022). "Therefore, our study findings support that CKAP2L is associated with poor prognosis of glioma, can be used as an independent risk factor, and has diagnostic value." (PMID 34631884, 2021). "To investigate whether CKAP2L can be used as an independent risk factor for poor prognosis of glioma, we analyzed the three transcriptome datasets by univariate and multivariate Cox analyses." (PMID 34631884, 2021). "Receiver operating characteristic (ROC) curve analysis was employed to determine whether CKAP2L has diagnostic value in the prognosis of glioma patients." (PMID 34631884, 2021). "Meanwhile, CKAP2L is a vital regulator of miR-4496 activity, and facilitates glioma cell proliferation, migration, invasion, and epithelial-mesenchymal transition." (PMID 36090903, 2022). "In glioblastoma cell line, a recent study confirmed that CKAP2L knockdown with siCKAP2L inhibited glioma cell proliferation, migration, invasion, and epithelial-mesenchymal transition." (PMID 35715760, 2022). "GSEA revealed that CKAP2L can regulate the development of glioma cells through various signaling pathways, especially that of the cell cycle." (PMID 34631884, 2021). "We further validated the influence of CKAP2L on patients with glioma by analyzing 40 clinical samples, consisting of both high-and low-grade glioma tissues, and the patient characteristics and outcomes." (PMID 34631884, 2021). "To further verify the CKAP2L expression profile in glioma, we examined CKAP2L protein levels in glioma data from The Human Protein Atlas, revealing markedly higher CKAP2L protein levels in low-grade and high-grade glioma tissues than in normal brain tissue." (PMID 34631884, 2021). "The results were consistent in thousands of tissue samples, reliably indicating that high expression levels of CKAP2L led to poor prognosis in glioma patients." (PMID 34631884, 2021). "The MTT and wound healing assays further demonstrated that CKAP2L influenced the proliferative and migratory abilities of glioma cells." (PMID 34631884, 2021). "Further, high expression of CKAP2L led to shorter survival times for both high-and low-grade glioma patients." (PMID 34631884, 2021). "Our findings elucidate the possible role of CKAP2L in glioma, identifying a reliable biological biomarker for its diagnosis and treatment." (PMID 34631884, 2021). "This is the first study to demonstrate that high CKAP2L expression leads to poor prognosis in glioma patients, providing a novel target for diagnosis and treatment of glioma." (PMID 34631884, 2021). "Based on the highest expression level of CKAP2L of U251 among the four glioma cell lines, we chose U251 cells to perform subsequent in vitro experiments." (PMID 34631884, 2021).
glioma (continued). "To confirm the impact of abnormally high expression of CKAP2L on the prognosis of glioma patients, we collected patient information from three different TCGA and CGGA transcriptome datasets and 40 clinical glioma patients." (PMID 34631884, 2021). "The main purpose of this study was to clarify the relationship between prognostic clinical characteristics of glioma patients and CKAP2L expression using data collected from the GEPIA, HPA, CGGA, TCGA, and GEO databases." (PMID 34631884, 2021). "Although we made every effort to elucidate the relationship between CKAP2L and the prognosis of glioma patients, the use of public databases has certain limitations, such as inconsistent clinical information across different databases." (PMID 34631884, 2021). "The results demonstrated that CKAP2L expression was higher in glioma tissues than in normal brain tissues at both the mRNA and protein levels." (PMID 34631884, 2021). "To further study the relationship between CKAP2L expression and prognosis of glioma, we analyzed three transcriptome datasets: CGGA microarray, CGGA RNA-seq, and TCGA RNA-seq." (PMID 34631884, 2021). "To investigate the impact of CKAP2L on mitotic function, we compared the cell cycle phase distributions between glioma cells expressing siCKAP2L and siControl." (PMID 33375517, 2020). "Because CKAP2L knockdown reduced cell proliferation, despite the increase in cells at the G2/M phase, we suggest that the glioma cells were arrested at the G2/M phase." (PMID 33375517, 2020). "After further breakdown by the tumor grading, we found the grade III glioma revealed a survival difference between the high and low CKAP2L expression groups at TCGA and CGGA datasets (p < 0.001 and p = 0.017, respectively)." (PMID 33375517, 2020). "In the present study, therefore, we used bioinformatic analysis, clinical validation, cell modeling, and miRNA screening to investigate the role played by CKAP2L in gliomas." (PMID 33375517, 2020). "We found that CKAP2L mRNA expression was significantly higher in all three glioma cell lines than in normal brain tissue (p < 0.001)." (PMID 33375517, 2020). "Using U87MG, U118MG, and LNZ308 human glioma cells, we confirmed that CKAP2L knockdown with siCKAP2L inhibits glioma cell proliferation, migration, invasion, and epithelial-mesenchymal transition." (PMID 33375517, 2020). "To assess the relation between CKAP2L and glioma-related genes and other factors, we performed univariate and multivariate analyses." (PMID 33375517, 2020). "Using a miRNA array to analyze miRNA expression in U87MG and U118MG glioma cells expressing siCKAP2L or siControl, we identified three miRNAs that were upregulated after CKAP2L knockdown in both cell types: miR-4496, miR-642b-3p, and miR-4740." (PMID 33375517, 2020). "To further explore CKAP2L mRNA and protein expression in glioma, we performed quantitative RT-PCR and Western blot analyses with normal brain tissue and the U87MG, U118MG, and LNZ308 human glioma cell lines." (PMID 33375517, 2020). "This suggests that suppressing CKAP2L led to increases in miR-4496, which reduced glioma cell proliferation." (PMID 33375517, 2020). "After transfection of siCKAP2L or siRNA (scramble siRNA) into U87MG and U118MG glioma cells, the expression of CKAP2L was substantially reduced at both 25 nM and 37.5 nM siRNA supplementation." (PMID 33375517, 2020). "From TCGA and CGGA glioma datasets, we noticed the difference in CKAP2L expression showed high significance (p < 0.0001) among the tumor grades." (PMID 33375517, 2020). "To evaluate CKAP2L protein expression in human glioma tissues, we immunostained tissue microarray slides containing gliomas of various WHO grades for CKAP2L." (PMID 33375517, 2020). "From bioinformatics analyses of datasets from The Cancer Gene Atlas and the Chinese Glioma Genome Atlas, we found that CKAP2L expression correlates with tumor grade and overall survival." (PMID 33375517, 2020).
glioma (continued). "The Oncomine database indicated that CKAP2L is highly expressed in bladder cancer, brain and central nervous system cancer, breast cancer, cervical cancer, colorectal cancer, gastric cancer, head and neck cancer, kidney cancer, liver cancer, lung cancer, lymphoma, melanoma, and ovarian cancer." (PMID 36699449, 2022). "We employed a variety of data fusion analyses, based on thousands of multiethnic tissue samples to improve the scientific rigor and credibility of our results, and further verified the expression of CKAP2L in collected clinical samples and commercial glioma cell lines." (PMID 34631884, 2021). "These genes also indirectly support the hypothesis that CKAP2L may promote the pathological process of glioma." (PMID 34631884, 2021). "Several drugs with potential inhibitory effects on CKAP2L were identified in the CMap database that may have therapeutic effects on glioma." (PMID 34631884, 2021). "Therefore, we verified that the increased expression level of CKAP2L in glioma in the database resulted in the decrease of overall survival time of glioma patients." (PMID 34631884, 2021). "Moreover, we examined the expression of CKAP2L in normal human astrocytes and four different glioma cell lines, determining the highest CKAP2L expression in U251 cells." (PMID 34631884, 2021). "To determine whether CKAP2L expression differs in glioma, we first investigated the expression of CKAP2L in glioma-related datasets obtained from GEPIA, HPA, and GEO." (PMID 34631884, 2021). "CKAP2L expression in glioma was significantly increased compared with that in normal brain tissue." (PMID 34631884, 2021). "Furthermore, CKAP2 acts as a significant paralog of CKAP2L, and the oncogenic nature and overexpression of this gene is revealed in PCa, ovarian cancer, and glioma." (PMID 33927744, 2021). "At present, there is only limited information about the role of CKAP2L in glioma." (PMID 33375517, 2020). "Likewise, expression of CKAP2L protein was higher in the three glioma cell lines than normal brain tissue." (PMID 33375517, 2020). "In the present study, we investigated the role of CKAP2L in glioma." (PMID 33375517, 2020). "Our findings indicate that CKAP2L is an important prognostic marker in glioma." (PMID 33375517, 2020). "Hence, it will be worthwhile to focus here and further clarify miR-4496/β-catenin signals with CKAP2L for the glioma in future work." (PMID 33375517, 2020). "Furthermore, an earlier study showed that downregulation of CKAP2L triggers multipolar spindles and cell cycle arrest, which is consistent with our present findings in glioma cells and tissues." (PMID 33375517, 2020). "Therefore, the high expression of CKAP2L may promote the proliferation of glioma cells through the activation of cell cycle signal pathway, which has been further verified." (PMID 34631884, 2021). "Given that U87MG and U118MG glioma cells exhibit higher CKAP2L mRNA expression than normal brain tissue, we next tested whether glioma phenotypes (increased proliferation, invasion, and migration) could be suppressed by knocking down CKAP2L expression using small interfering RNA (siRNA)." (PMID 33375517, 2020). "We therefore hypothesized that CKAP2L may play similar roles in glioma." (PMID 33375517, 2020). "Thus, the effect of miR-4496 on glioma cell proliferation was similar to that of CKAP2L knockdown." (PMID 33375517, 2020). "Moreover, by manipulating miR-4496, one may be able to suppress the oncogenic effects of CKAP2L, which may be a potentially useful addition to the treatments for glioma." (PMID 33375517, 2020). "Using shRNA to knock down the expression of CKAP2L, we then performed MTT and wound healing assays to investigate the effect of CKAP2L on the biological characteristics of glioma cells." (PMID 34631884, 2021). "Through gene correlation analysis, we identified genes positively correlated with CKAP2L, including BUB1, TTK, and ASPM, which can promote the development of glioma and treatment resistance." (PMID 34631884, 2021).
glioma (continued). "However, to date, CKAP2L has not been reportedly associated with glioma." (PMID 34631884, 2021). "Next, to further model the consequence of the CKAP2L expression on the cell cycle, we examined the effect of CKAP2L knockdown on the cell cycle profile in U87MG and U118MG glioma cells." (PMID 33375517, 2020). "To further understand the impact of the CKAP2L expression on cell growth, we investigated the effect of CKAP2L knockdown on the proliferation in U87MG and U118MG glioma cells." (PMID 33375517, 2020). "Recent studies have found that cytoskeleton-associated protein 2 like (CKAP2L), an important oncogene, is involved in the biological behavior of many malignant tumors, but its function in the malignant course of glioma has not been confirmed." (PMID 34631884, 2021). "Therefore, this study was aimed at exploring the previously unknown relationship between CKAP2L and the biological characteristics of glioma patients, based on clinical sample analysis of multiple databases, and at confirming the oncogenic role of CKAP2L in glioma." (PMID 34631884, 2021). "Similarly, among the 325 glioma samples in the CGGA dataset, CKAP2L mRNA expression correlated significantly (p < 0.0001) with the tumor grade." (PMID 33375517, 2020). "However, it is worth noting that the relationship between CKAP2L and the prognostic features of gliomas has not been elucidated and revealed." (PMID 34631884, 2021). "Up to now, the role of CKAP2L in gliomas has not been addressed." (PMID 33375517, 2020).
breast carcinoma (6 papers, 2021 to 2025). "A breast cancer study has shown that CKAP2L activates the AKT/mTOR signaling pathway and thus promotes breast cancer development." (PMID 37225919, 2023).
Filippi syndrome (6 papers, 2017 to 2025). Filippi syndrome is characterized by microcephaly, cutaneous syndactyly of the fingers and toes, intellectual deficit, growth retardation and a characteristic facies (high and broad nasal bridge, thin alae nasi, micrognathia and a high frontal hairline). "Mutations in the gene encoding cytoskeleton-associated protein 2-like (CKAP2L) have been identified as a causative factor for Filippi syndrome, a rare developmental disorder characterized by facial dysmorphism, syndactyly, and microcephaly." (PMID 41370039, 2025). "Mutations in CKAP2L have been shown to cause a rare genetic disease called Filippi syndrome, which highlights the important role of CKAP2L in neurogenesis." (PMID 39073037, 2024). "For identifying the disease-causing variant(s) in family 1, the following strategy was adopted; due to phenotypic overlap of patient 1 with Filippi syndrome, we first excluded pathogenic variants in CKAP2L by Sanger sequencing." (PMID 35571680, 2022). "Filippi syndrome is usually caused by mutations in the mitotic spindle protein cytoskeleton associated protein 2-like (CKAP2L) and is characterized by microcephaly, short stature, syndactyly, intellectual disability, and facial dysmorphism (OMIM 272440)." (PMID 28161493, 2017). "In 2014, it was reported that mutations in a previously unknown gene, cytoskeleton‐associated protein 2‐like (CKAP2L), cause Filippi syndrome, a rare genetic disorder characterized by microcephaly and mental retardation." (PMID 39073037, 2024). "Furthermore, loss of function of CKAP2L causes Filippi syndrome and microcephaly." (PMID 36090903, 2022). "Collectively, these findings position CKAP2L as a multifunctional regulator of microtubule-based organelles and propose that Filippi syndrome can be classified as a 'centrosomopathy' arising from concurrent defects in cell proliferation and ciliary function." (PMID 41370039, 2025). "Studies on CKAP2L are currently focused on Filippi syndrome, rather than tumors." (PMID 32090084, 2020).
lung adenocarcinoma (6 papers, 2019 to 2024). A carcinoma that arises from the lung and is characterized by the presence of malignant glandular epithelial cells. "The high expression of CKAP2L in lung adenocarcinoma was found to be associated with the tumor stage, lymph node status, and metastasis." (PMID 32090084, 2020). "The ’Cytoskeleton Associated Protein 2 Like’ (CKAP2L) protein is localized on microtubules of the spindle pole throughout metaphase to telophase in wild-type cells, and a knock-down of CKAP2L has been found to suppresses migration, invasion, and proliferation in lung adenocarcinoma." (PMID 31438847, 2019). "Others reported that depletion of CKAP2L suppressed proliferation, migration, and invasion of lung adenocarcinoma cells, including H460, A549, and H1299." (PMID 39073037, 2024). "More recently, studies have identified CKAP2L as a prognostic marker of various human cancer, including esophageal squamous cell carcinoma, hepatocellular carcinoma, lung adenocarcinoma, and clear cell renal carcinoma." (PMID 39073037, 2024). "A recent paper reports high expression of CKAP2L, which induces the invasion of lung adenocarcinoma by the MAPK signaling pathway, and shows correlation with poor prognosis." (PMID 33927744, 2021). "Indeed, recent studies have shown that CKAP2L level is elevated in many types of human cancer, including esophageal squamous cell carcinoma, hepatocellular carcinoma, lung adenocarcinoma, and clear cell renal carcinoma." (PMID 39073037, 2024). "It has been reported that CKAP2L may act on the proliferation, migration, and invasion of lung adenocarcinoma cells through mitogen-activated protein kinase (MAPK) signaling pathway, but its role in other tumors has yet to be fully studied." (PMID 32090084, 2020).
lung carcinoma (5 papers, 2020 to 2023). "Concurring with our results, studies with liver, prostate, and lung cancers have reported that high expression of CKAP2L is associated with poor prognosis in tumor patients and can be used as a marker for diagnosis and treatment." (PMID 34631884, 2021). "Cytoskeleton-associated protein 2-like (CKAP2L), which plays key roles in neural progenitor cell division, has also been linked to poor prognosis in lung cancer." (PMID 33375517, 2020).
glioblastoma (4 papers, 2020 to 2023). The most malignant astrocytic tumor (WHO grade IV). "In prostate cancer, esophageal squamous cell carcinoma and glioblastoma, CKAP2L has been shown to affect the biological behavior of cancer cells by regulating the cell cycle." (PMID 37225919, 2023).